LEPR (leptin receptor)
Diseases named in the same sentence as LEPR in open-access papers (continued):
Sharing a sentence is not in itself a finding about the gene and the disease.
Infertility (28 papers, 2010 to 2025). "Knock-out LEPR mice have small testes, azoospermia, and multinucleated spermatids, while patients with LEPR gene mutations are infertile." (PMID 37662867, 2023). "Women suffering from mutations in leptin or LEPR can be infertile due to low levels of follicle-stimulating and luteinizing hormones, leading to the loss of pubertal maturity and hypogonadotropic hypogonadism." (PMID 33922961, 2021). "Since db/db and ob/ob mice are infertile, genetically engineered mouse models with simultaneous mutations in Mst1 and the leptin receptor are poorly accessible, while STZ-induced DCM models are widely used." (PMID 33953853, 2021). "LepR tyrosine site mutation mice (Y123F) exhibit decreased serum E2 levels, immature reproductive organs, infertility as well as metabolic abnormalities." (PMID 29728128, 2018). "We show that we can cause infertility in 70% of female mice by deleting all isoforms of LEPR specifically in gonadotropes." (PMID 29354094, 2017). "It is well recognized that a mutation in the leptin receptor gene (Lepr) causes infertility in the homozygous state." (PMID 23671847, 2013). "Last decades, particular attention was paid to the effect of leptin on reproduction, especially on the gonadal dysfunction as infertility, a characteristic feature of both ob/ob (leptin deficient) and db/db (leptin receptor mutant) mice." (PMID 23803253, 2013). "Besides hunger and satiety, the loss of LEPR function causes infertility, accelerated growth, disrupted pubertal development, metabolic disorders such as insulin resistance, impaired thyroid and immune function." (PMID 33922961, 2021). "Deleting all isoforms of leptin receptor (LEPR) in gonadotropes causes infertility." (PMID 29354094, 2017). "The diagnostic sensitivity and specificity of GLUT4, LEPR, and TNF-α combined assay for PCOSinduced infertility in PCOS women were 88.57% and 75.00%, respectively, and those for PCOS in healthy women were 78.57% and 60.00%, respectively (P<0.05)." (PMID 39991169, 2025). "GLUT4, LEPR, and TNF-α levels in the peripheral blood were detected in all participants, and their diagnostic value for PCOS in healthy women and PCOS-induced infertility in PCOS patients was analyzed." (PMID 39991169, 2025). "The results of this study showed that rs1137101 polymorphism of the LEPR gene is associated with PCOS and PCOS-related infertility." (PMID 34407095, 2021). "According to the results of this study and other research, it can be assumed that the association of LEP and LEPR variants with PCOS–and also PCOS-related infertility and RPL- is dependent on the ethnic/racial background of the study population." (PMID 34407095, 2021). "LEP (rs7799039) and LEPR (rs1137101) polymorphisms and the risk of PCOS, PCOS-infertile, and PCOS-RPL." (PMID 34407095, 2021). "In contrast, expression of the leptin receptor specifically in the PMV region of LepR mutant mice restores fertility to these normally infertile mice." (PMID 30917148, 2019). "This resulted in unreliable breeding or infertility, which supports our assertions that gonadotrope LEPR is important to the HPG axis." (PMID 29354094, 2017). "Leptin knockout (ob/ob) or leptin receptor knockout (db/db) mice display reproductive deficits and infertility." (PMID 22132231, 2011). "RT-PCR revealed the absence long isoform of Leptin receptor expression in 20 out of 23 infertile individuals and a weak expression in 1 out of 10 fertile individuals." (PMID 20178606, 2010). "There are conflicting reports about presence of Leptin receptor in human sperm, therefore, the aim of this study was to evaluate presence of Leptin receptor in fertile and infertile males at both mRNA and protein levels." (PMID 20178606, 2010). "Thus, overexpression of the leptin receptor by Leydig cells appears to inhibit testosterone production in infertile men, suggesting that signaling transduction pathway(s) downstream of leptin exert negative control over steroidogenesis by human Leydig cells." (PMID 35246515, 2022).
Infertility (continued). "Moreover, mice and humans missing leptin receptor were reported to acquire hypothalamic hypogonadism, which delays puberty and results in infertility." (PMID 32082253, 2019). "In addition, the ablation of the leptin receptor from all forebrain neurons prevented the onset of puberty and induced infertility in male and female mice, whereas selective deletion of the leptin receptor from GnRH neurons resulted in normal fertility." (PMID 29976877, 2018). "Previous studies report an inverse correlation between leptin receptor expression by Leydig cells and the serum testosterone concentration in human testis, which suggested that over- expression of leptin receptor in Leydig cells leads to inhibition of testosterone production in infertile men." (PMID 20178606, 2010). "In conclusion, these data showed a more severe infertility phenotype in mice lacking all isoforms of LEPR in gonadotropes." (PMID 29354094, 2017). "Consequently, POMC neurons as a target of leptin/insulin actions were shown to be important for fertility, as IR/LEPR-POMC KO mice exhibit lengthened reproductive cycles, follicular arrest, hyper-androgenemia, and infertility." (PMID 27146259, 2016). "Kiss1-Cre LepR null mice showed no pubertal development and no improvement of the metabolic phenotype, remaining obese, diabetic and infertile." (PMID 23505551, 2013). "Flow cytometry and western blot analysis were carried out on 10 fertile and 20 infertile individuals which also revealed the absence of Leptin receptor on the sperm of fertile and infertile individuals." (PMID 20178606, 2010). "Accordingly, it was not unexpected to see the lack of leptin receptor expression in both fertile and infertile individuals in this study." (PMID 20178606, 2010). "Unlike PBMCs (positive control), spermatozoa from fertile and infertile individuals were negative for the leptin receptor extracellular domain after incubation with an anti-leptin-receptor antibody." (PMID 20178606, 2010). "Additionally in this study, RT-PCR analysis showed a lack of leptin receptor expression in 29 out of 33 infertile and fertile individuals." (PMID 20178606, 2010). "The total number of samples which assessed for leptin and leptin receptor levels was 177 (non-PCOS = 49, PCOS-RPL = 70 and PCOS-infertile = 58)." (PMID 34407095, 2021).
Bardet-Biedl syndrome (26 papers, 2014 to 2025). A ciliopathy with multisystem involvement. "POMC, PCSK1, and LEPR deficiencies and Bardet-Biedl syndrome (BBS) can be counter-regulated by the MC4R agonist setmelanotide." (PMID 40822950, 2025). "Informed by these mechanistic studies, successful phase 3 clinical trials have led to a second generation MC4R agonist being licensed in many countries for the treatment of several monogenic disorders (POMC, PCSK1, LEPR deficiencies and Bardet-Biedl Syndrome (BBS))." (PMID 37661743, 2023). "Approved from age 2, but limited to specific genetic disorders (e.g., biallelic POMC, LEPR, Bardet-Biedl syndrome), and may be used in this age range (genotype-restricted)." (PMID 41212412, 2025).
Glucose intolerance (23 papers, 2010 to 2025). Glucose intolerance (GI) can be defined as dysglycemia that comprises both prediabetes and diabetes. "The db/db mouse is a recognized animal model with over-weight, severe glucose intolerance, and fatty liver due to the leptin receptor-deficiency." (PMID 28534819, 2017). "In support, we recently showed that subordination stress aggravates glucose intolerance in leptin receptor mutant db/db mice." (PMID 26946982, 2016). "Morioka and colleagues further confirm that mice with specific disruption of leptin receptor in pancreatic β cells develop more severe glucose intolerance when fed a high-fat diet due to impaired insulin secretion from β cells." (PMID 21113299, 2010). "The db−/+ model of gestational diabetes, on the other hand, has similarities to our model including glucose intolerance that develops mid-gestation, however, the phenotype is induced by genetic deletion of the leptin receptor, a different pathoetiology relative to our model." (PMID 33772108, 2021). "POMC-specific loss of LEPR or ATG7 increased body weight in both sexes, but only male pomc-LepR KO mice and female pomc-ATG7 KO mice developed glucose intolerance." (PMID 36120438, 2022).
hyperlipidemia (21 papers, 2012 to 2025). "The ZDF rat is a recognized T2DM animal model characterized with overweight, impaired glucose tolerance and hyperlipidemia due to the leptin receptor mutation." (PMID 34093169, 2021). "Adult ZDF rats develop hyperlipidemia, hyperglycemia, hyperinsulinemia, insulin resistance, fatty liver and hepatocyte degeneration owing to an inherited mutation of the leptin receptor." (PMID 31749893, 2019). "In the ZDF rat model, leptin receptor gene mutation is a complicated scenario leading to rather severe hyperlipidemia." (PMID 31749893, 2019). "We investigated the associations of LEP G2548A and LEPR Q223R polymorphisms with statin-induced creatine kinase (CK) elevation among Chinese patients with hyperlipidemia." (PMID 29296187, 2017). "In this study, we examined the differences in leptin, leptin receptor, total cholesterol, and triglyceride levels between healthy dogs and dogs with cholelithiasis, and evaluated the correlation between leptin and hyperlipidemia." (PMID 29088261, 2017). "Previous reports have established that the absence of leptin receptor induces hyperlipidemia, hypercholesterolemia, hepatic fat accumulation and NAFLD in corpulent JCR rats." (PMID 25222487, 2014).
Anxiety (20 papers, 2012 to 2025). Intense feelings of nervousness, tension, or panic often arise in response to interpersonal stresses. "Instead, VTA LepR neurons primarily project to the central amygdala, and these neurons mediate effects of leptin on central amygdala associated behaviors, such as anxiety." (PMID 34276560, 2021). "Clearing senescent cells from high fat-fed or leptin receptor-deficient obese mice restored neurogenesis and alleviated anxiety-related behavior." (PMID 34901108, 2021). "LEPR haplotypes in the European American group were also significantly associated with measures of cigarette smoking as well as anxiety." (PMID 34421692, 2021). "In summary, our results suggest that LEP and LEPR are linked to some measures of substance use and anxiety." (PMID 34421692, 2021). "Overall, this study found that variations in the leptin and leptin receptor genes are associated with measures of alcohol use, nicotine use, and anxiety." (PMID 34421692, 2021). "Together, our transcriptional analysis suggests that at least two, molecularly distinguishable, LepRLH subpopulations have dissociable roles in the adaptive regulation of anxiety behavior, whereby Ebf1 expression in LepR subpopulation may be associated with reduced anxiety." (PMID 41116115, 2025). "Systemic administration of leptin has been shown to produce anxiolytic effects and removal of the leptin receptor in midbrain dopaminergic neurons results in an anxiety-like phenotype." (PMID 39559273, 2024). "Removal of LepR signaling (by removing Stat3) from dopamine neurons results in hyperactivity in male mice and leads to anxiety in females." (PMID 40656109, 2024). "More specfically, removal of LepR from dopamine neurons (in Dat-Cre mice) also increases anxiety in the elevated plus maze, and is restored by blocking D1 receptors in CeA." (PMID 40656109, 2024). "In leptin receptor-null obese mice (db/db vs. db/+), chronic food restriction or anti-inflammatory treatment reduced anxiety-like behavior and hippocampal and/or peripheral inflammation, but anti-inflammatory treatment did not reverse the obese state." (PMID 37443828, 2023). "We directly compared behavioral effects of chemogenetically activating VTA LepR or SN LepR neurons on motivational behavior for food reward, feeding, locomotion and anxiety in LepR-cre mice." (PMID 34276560, 2021). "Glucose utilization was activated by binding of AAC2 to alternative sites on the leptin receptor (LepR) and was sufficient to treat mice with T1D and T2D, and to reduce anxiety in diabetic mice." (PMID 35056977, 2021). "Low-anxiety animals as tested in the EPM tended to have larger LepR+ Ebf1+ populations." (PMID 41116115, 2025). "To test whether Ebf1 coexpression with LepR in LH neurons is relevant for anxiety behavior, we transfected LepRLH neurons with mCherry, measured anxiety behavior in both the EPM and the OF test and costained LepRLH neurons for Ebf1." (PMID 41116115, 2025). "Furthermore, leptin injected into the VTA reduces anxiety-like behaviors, and removal of LepR (using AAV-cre technology) from VTA enhanced anxiety-like behaviours." (PMID 40656109, 2024). "Leptin receptor alterations were identified in the cerebral region of the amygdala, one of the regions involved in regulating the pleasure and reward sensations; identification of a dangerous situation; and emotional control, mainly of anxiety and fear." (PMID 38362276, 2024). "Furthermore, increased anxiety was seen after deletion of LepR in DA neurons and this was accompanied by increased burst firing of VTA DA neurons." (PMID 34276560, 2021). "Finally, because previous studies showed that VTA LepR modulated anxiety, we aimed to verify this in our experiments and determined effects of activating VTA LepR or SN LepR on anxiety-like behavior." (PMID 34276560, 2021).
Anxiety (continued). "As the midbrain dopamine system has been implicated in these behaviors as well, we here addressed whether selective chemogenetic activation of leptin receptor expressing midbrain neurons modulated feeding, locomotion, anxiety and motivation." (PMID 34276560, 2021). "When assessing anxiety-like behavior in the EPM in the mice in our study, we found that both BACHD and BACHD/LepR-cre spent less time and made fewer entries onto the open arms, indicative of an anxiety-like phenotype." (PMID 23251447, 2012). "We observed a similar negative correlation between LepR+Ebf1+ coexpression (assessed using multilabeling in situ hybridization) and anxiety as tested in the EPM." (PMID 41116115, 2025). "Next, two questions were of particular interest for behavioral experiments: 1) whether SN LepR neurons modulate motivational, locomotor and feeding behavior and 2) whether VTA LepR neurons mediate anxiety-like, feeding and locomotor behavior." (PMID 34276560, 2021). "Together, these data suggest that VTA (DA) LepR neurons modulate anxiety-like and not motivational behavior." (PMID 34276560, 2021). "Together, these results suggest that chemogenetic activation of VTA LepR neurons did not activate VTA DA neurons to the extent of burst firing that is capable of increasing anxiety." (PMID 34276560, 2021). "Our results show that inactivation of mutant HTT in leptin receptor-expressing neurons in the BACHD mouse using cross-breeding based on a cre-loxP system did not have an effect on the metabolic phenotype or anxiety-like behavior." (PMID 23251447, 2012). "Together, our data suggest that the anxiolytic role is specific to LepRLH neurons, which may include an anxiety-responsive subset of the LepR+ Gal+ subpopulation, but not NtsLH or CrhLH populations." (PMID 41116115, 2025). "We did not observe changes in anxiety-like behavior upon chemogenetic activation of VTA LepR." (PMID 34276560, 2021). "However, the BACHD/LepR-cre mice did not spent significantly more time than BACHD mice on the open arms indicating that inactivation of mutant HTT selectively in LepR neurons did not have an effect on the development of anxiety-like behavior in BACHD mice." (PMID 23251447, 2012). "In female mice lacking LepR signaling on dopamine neurons (not exposed to ABA), a D1 antagonist in the CeA normalized the increased anxiety." (PMID 40656109, 2024).
morbid obesity (20 papers, 2010 to 2022). An excess of body weight, normally defined as an individual with a body mass index greater than 35 or a body weight greater than one hundred percent of ideal body weight. "In mammals, leptin (ob/ob) and leptin receptor (db/db) deficiencies lead to excessive hyperphagia, morbid obesity, and a diabetic phenotype." (PMID 35454105, 2022). "Several studies have reported that mutations in the genes encoding leptin (LEP) and its receptor (LEPR) have been associated with hyperphagia and morbid obesity." (PMID 28428959, 2017). "In the present study we explored the association of six LEPR gene polymorphisms in patients with morbid obesity." (PMID 28096764, 2016). "It has also been found that mutations of the LEPR gene results in leptin insensitivity, hyperphagia, morbid obesity, as well as metabolic and endocrine abnormalities." (PMID 26365669, 2015). "In collaboration with Antje Körner, we recently found that heterozygosity of newly identified LEPR variants may contribute to the development of childhood morbid obesity." (PMID 34390703, 2021). "At high levels, leptin inhibits food intake through the melanocortin receptor system, and at low levels, it promotes food intake through neuropeptide Y. Mutations in the LEPR gene result in leptin insensitivity, hyperphagia, morbid obesity, and metabolic and endocrine abnormalities." (PMID 31480192, 2020). "Adipose hormone leptin critically regulates body weight and metabolism, and disruption of leptin/leptin receptor (LepR) signaling results in morbid obesity and severe metabolic disease." (PMID 32251290, 2020). "The hormone leptin, discovered in 1994, critically regulates body weight and metabolism at central level in the brain, and disruption of leptin/leptin receptor (LEPR) signaling results in morbid obesity and severe metabolic disease." (PMID 32630697, 2020). "While mouse models with deficient IL-6 signaling show an ameliorated but not absent Diethylnitrosamine (DEN)-induced HCC development, the morbid obesity in mice with mutant leptin signaling complicates the dissection of hepatic leptin receptor (LEPR) and IL-6 signaling in HCC development." (PMID 30224299, 2018). "Thus, unlike neurosensory hearing loss or anosmia, metabolic defects are not typically considered as primary events in CHH, apart from syndromic CHH caused by LEP, LEPR, or PCSK1 mutations resulting in both GnRH deficiency and morbid obesity." (PMID 28754744, 2017). "In this work we explored the association of several LEPR gene polymorphisms with morbid obesity compared with non-obese Mexican Mestizo adults." (PMID 28096764, 2016). "Our results suggest that rs1805134 polymorphism could be involved in the development of morbid obesity, whilst none of the alleles of the LEPR gene, rs1137100, rs1137101, rs1805094 and rs1805096 were associated as risk factors." (PMID 28096764, 2016). "Furthermore, no deleterious mutations were found in genes known to cause morbid obesity such as leptin, leptin receptor, melanocortin 4 receptor, POMC, adiponectin and adiponectin receptor." (PMID 23300646, 2012).